SCEL (sciellin)
Description:
May function in the assembly or regulation of proteins in the cornified envelope. The LIM domain may be involved in homotypic or heterotypic associations and may function to localize sciellin to the cornified envelope.
Synonyms: FLJ21667; MGC22531
Tractability: Antibody: its Gene Ontology location is reachable by antibodies, with high confidence; the Human Protein Atlas places it where antibodies can reach.
Gene: Protein-coding gene on chromosome 13 (77,535,605 to 77,646,769, forward strand). Ensembl gene ENSG00000136155.
Subcellular location: Cytoplasm; Membrane
Subcellular location (Human Protein Atlas): Plasma membrane; Cytosol; Nucleoplasm
Gene Ontology:
Molecular function: protein binding
Biological process: keratinocyte differentiation; positive regulation of canonical Wnt signaling pathway; response to mechanical stimulus; embryo development ending in birth or egg hatching; epidermis development
Cellular component: cytoplasm; cytosol; extracellular exosome; nucleoplasm; perinuclear region of cytoplasm; plasma membrane; cornified envelope; membrane
Genetic constraint (gnomAD): Loss-of-function variants: 18 observed, 17.73 expected, observed/expected ratio (o/e) 1.01, 90% interval 0.7 to 1.5. The upper end of that interval is the gene's LOEUF score, 1.5, which puts it in group 6 of 6, group 1 being the genes least tolerant of losing a copy. Missense variants: 194 observed, 212.69 expected, observed/expected ratio (o/e) 0.91, 90% interval 0.81 to 1.03. Synonymous variants: 67 observed, 69.22 expected, observed/expected ratio (o/e) 0.97, 90% interval 0.79 to 1.19.
Homologues: Orthologues: chimpanzee SCEL (98% identical), macaque SCEL (93% identical), rabbit SCEL (77% identical), dog SCEL (77% identical), pig SCEL (76% identical), rat Scel (66% identical), mouse Scel (64% identical), tropical clawed frog scel (30% identical). Paralogues in human: ZNF185 (16% identical).
Diseases named in the same sentence as SCEL in open-access papers:
SCEL is named in the same sentence as 28 diseases in open-access papers, as found by Europe PMC text mining. Sharing a sentence is not in itself a finding about the gene and the disease. The quoted sentences say what the papers report.
colorectal cancer (3 papers, 2016 to 2021). A primary or metastatic malignant neoplasm that affects the colon or rectum. "One of them, sciellin, a precursor of the cornified envelope, has been found to mediate mesenchymal-to-epithelial transition and knockdown of sciellin increase invasion and migration of colorectal cancer cells." (PMID 34283070, 2021). "Recently, it has been reported that overexpression of SCEL inhibited cell migration and invasion in colorectal cancer cells, and it mediates mesenchymal-to-epithelial transition via activating Wnt signaling." (PMID 31974341, 2020). "Sciellin (SCEL), a precursor to the cornified envelope of human keratinocytes, has been shown to inhibit migration and invasion capabilities of colorectal cancer cells." (PMID 31974341, 2020). "To evaluate SCEL expression in clinical samples, we performed immunohistochemical staining (IHC) with anti-SCEL antibody on the colorectal cancer tissue array CO1501 (US Biomax)." (PMID 27013588, 2016). "The characteristics of SCEL make it a suitable target candidate for low side effect targeted therapies to prevent or eliminate colorectal cancer metastasis." (PMID 27013588, 2016). "We determined the expression of SCEL in clinical specimens to further confirm its disease relevance and found SCEL in the early stages of colorectal cancers." (PMID 27013588, 2016). "Although it acts as a MET inducer, SCEL is highly expressed in primary colorectal cancer before metastasis onset." (PMID 27013588, 2016). "In addition, SCEL showed a higher ratio of expression in the later stages of colorectal cancer, suggesting SCEL expression correlates with cancer progression." (PMID 27013588, 2016). "Since SCEL is originally expressed in primary colorectal cancer tissue, we wondered whether SCEL expression was dynamically regulated during metastasis." (PMID 27013588, 2016).
breast carcinoma (2 papers, 2016 to 2023). "In the future, our study could be expanded to investigate the role of SCEL in other subtypes of breast cancer and in other types of cancer with a propensity for lung metastasis." (PMID 38037106, 2023). "Thus, SCEL may be a crucial stress-responsive protein that helps metastatic breast cancer cells overcome the unfavorable growth condition during early stage of lung colonization." (PMID 38037106, 2023). "Furthermore, the study could be expanded to investigate the role of SCEL in other subtypes of breast cancer and in other types of cancer with a propensity for lung metastasis." (PMID 38037106, 2023). "Since SCEL acts as a MET inducer, it is expected to be found in higher levels at the metastatic site relative to primary tumor, like the expression of the key MET mediator E-cadherin in breast cancer and prostate." (PMID 27013588, 2016).
gallbladder cancer (2 papers, 2021). "Roles of SCEL in gallbladder cancer cell were determined by molecular and cell biology methods." (PMID 33414368, 2021). "Our study is the first identify that SCEL can promote gallbladder cancer cell proliferation by EGFR/PI3K/AKT pathway, and SCEL can influence neutrophil extracellular traps formation through EGFR/IL8 axis." (PMID 33414368, 2021).
melanoma (2 papers, 2024 to 2025). A malignant, usually aggressive tumor composed of atypical, neoplastic melanocytes. "The enrichment of these categories reflects the dysregulation of transcriptional programs typical of keratinocytes (e.g., SPRR1/2/3, KRT10/KRT16, LOR, IVL, EVPL, SCEL, TGM1/TGM3, CERS3, ACER1, DSP) and, above all, the epithelial crosstalk that influences melanoma biology." (PMID 41465101, 2025). "Regarding SCEL, identified as a precursor of the cornified envelope in keratinizing tissues, our finding of its down-regulation in HNSCC aligns with observations in melanoma, where lower expression correlated with poor overall survival." (PMID 39596132, 2024).
metastatic cancer (2 papers, 2016). A carcinoma which has spread from the original site of growth to another anatomic site. "Two amplified genes had contradictory functions to being overexpressed in metastatic cancer, SCEL (a keratinocyte differentiation factor), and MPDZ (a cell adhesion factor)." (PMID 27136531, 2016). "Notably, SCEL protein levels were higher in hepatic metastatic cancer cells L1 and L2, implying that SCEL specifically contributes to CRC hepatic metastasis." (PMID 27013588, 2016).
pancreatic cancer (2 papers, 2021 to 2024). "SCEL is a potential biomarker for the prognosis of pancreatic cancer confirmed by Cheng et al27." (PMID 33731794, 2021). "A novel 14-gene signature comprising CCDC148, SH3RF2, CACNA1D, POLD3, PARP1, AP1M2, C4orf19, ANO1, VGLL1, SCEL, INPP4B, NET1, INSIG2 and BVES and a corresponding risk score formula were established for pancreatic cancer risk stratification and prognosis prediction." (PMID 33731794, 2021). "However, SCEL expression might seem to vary depending on cancer type, as it has been found in gallbladder and pancreatic cancers." (PMID 39596132, 2024).
bladder cancer (1 paper, 2019). "And thirdly, we firstly identified a set of 4 genes (TMPRSS11E, SCEL, KRT78, TMEM185A) that were significantly associated with poor overall survival of bladder cancer patients, some of which have not been investigated in urinary bladder cancer before." (PMID 31737111, 2019).
Cholecystitis (1 paper, 2021). The presence of inflammatory changes in the gallbladder. "SCEL was overexpressed in tumor tissues and rarely expressed in the cholecystitis count parts." (PMID 33414368, 2021).
esophageal cancer (1 paper, 2024). A primary or metastatic malignant neoplasm involving the esophagus. "The positively correlated genes (SLUT2B1, PPL, KLK6, CRYBG2, SCEL, ADGRF4 and KLK8) were more frequently expressed in esophageal cancer than normal tissue (p < .05)." (PMID 38241178, 2024).
lung adenocarcinoma (1 paper, 2024). A carcinoma that arises from the lung and is characterized by the presence of malignant glandular epithelial cells. "Furthermore, CBX8-PRC1 promotes lung adenocarcinoma growth and metastasis through transcriptional repression of CDKN2C and SCEL." (PMID 38816356, 2024).
lymph node metastasis (1 paper, 2016). "IHC on clinical specimens from CMUH indicated that SCEL was expressed in 81.0% (17/21 cases) of CRC specimens with lymph node metastasis and in 82.4% (14/17 cases) of CRC specimens with hepatic metastasis, consistent with the previous finding that SCEL expression correlated with cancer malignancy." (PMID 27013588, 2016).
metastatic tumors (1 paper, 2023). "Blocking the TNF-α-mediated survival pathway by adalimumab may be an effective therapy for SCEL-positive TNBC patients with pulmonary metastatic disease." (PMID 38037106, 2023).
papillary thyroid carcinoma (1 paper, 2020). "SCEL is overexpressed in the papillary thyroid carcinoma and worked as key regulator in mesenchymal-to-epithelial transition and dynamically regulated through the metastasis process." (PMID 32164602, 2020).
schizophrenia (1 paper, 2021). A major psychotic disorder characterized by abnormalities in the perception or expression of reality. "SCEL encodes sciellin, not an obvious schizophrenia candidate gene as it is expressed almost exclusively in the skin, tongue, and tonsils, and functions in assembling the cornified envelope of mammalian keratinizing tissues." (PMID 33159203, 2021).
squamous cell carcinoma of esophagus (1 paper, 2017). "We previously identified a single nucleotide mutation of SCEL gene in both normal and squamous cell carcinoma of esophagus in African-Americans." (PMID 28629367, 2017).
tongue squamous cell carcinoma (1 paper, 2017). A squamous cell carcinoma that arises from the tongue. "In our present study, SCEL is significantly under-expressed in African-American ESCC, and thus could play a role in squamous cell carcinogenesis as suggested by the down-regulation of this gene in larynx and hypopharynx, and in tongue squamous cell carcinoma." (PMID 28629367, 2017).
venous thromboembolism (1 paper, 2021). Occlusion of the lumen of a vein by a thrombus that has migrated from a distal site via the blood stream. "This study aimed to investigate the mechanistic role of Sciellin (SCEL) in GBC cell proliferation and the development of venous thromboembolism." (PMID 33414368, 2021).
cancer (7 papers, 2012 to 2024). A tumor composed of atypical neoplastic, often pleomorphic cells that invade other tissues. "3D collagen gel culture assay revealed that SCEL knockdown caused cancer cells to form more invasive structures compared to the compact sphere of control cells." (PMID 27013588, 2016). "SCEL knockdown also caused cancer cells to form more invasive structures within 3D cultures, increased the mesenchymal marker vimentin, and attenuated the epithelial marker E-cadherin." (PMID 27013588, 2016). "IHC illustrates that the percentage of cell expressing SCEL were 22.7%, 42.1%, 64.2%, and 63% in cancer stage I, II, III, and IV of CRC, respectively, revealing SCEL expression correlates with cancer malignancy." (PMID 27013588, 2016). "Due to the potential role of SCEL in cancer metastasis, we wondered whether SCEL was involved in regulation of the Wnt signaling pathway." (PMID 27013588, 2016). "CP, SCEL, and MUC16 had positive coefficients with a log2 ratio >1 for advanced T, N stage and perineural invasion cancer tissue." (PMID 28423673, 2017). "As a result, we found 3 novel candidate genes (CP, SCEL, and MUC16), having positive coefficients with a log2 ratio >1 for advanced T, N stage and perineural invasion cancer tissue." (PMID 28423673, 2017). "In the current study, we demonstrated that SCEL is dynamically regulated under TGF-β1 treatment and hypoxic condition, which are known to promote the mesenchymal phenotype and cancer cell invasiveness." (PMID 27013588, 2016). "SCEL has several features of a MET inducer, including promoting epithelial phenotype and increasing epithelial molecular marker expression as well as reducing cancer cell migration and invasion abilities." (PMID 27013588, 2016). "As expected, several of the top 10 up-regulated genes in ND (compared to T) were related to formation of the epidermis (e.g. TGM3 and SCEL) and were not altered in cancer." (PMID 22280838, 2012).
tumor (4 papers, 2016 to 2023). "The xenograft mouse model experiments revealed that knockdown of SCEL resulted in increase of caspase-3 activity, and decrease of ki67 and TNFR1 expression as well as increase of tumor-associated macrophages in the metastatic lung lesions." (PMID 38037106, 2023). "In this study, we found that SCEL stimulates multiple cytokine expression in tumor cells, in which IL-8 was found to promote neutrophils to develop NETs in vitro, consistent with previous reports that IL-8 is an essential factor in the formation of NETs46." (PMID 33414368, 2021). "Analogous to the EGFR signaling blockade, both EGFR and PI3Kα siRNA or inhibitors attenuated cell proliferation induced by SCEL, suggesting that SCEL acts as a tumor-promoting factor by activating EGFR-PI3K-Akt signaling." (PMID 33414368, 2021). "Next, we examined the protein expression of SCEL in TNBC tumor specimens." (PMID 38037106, 2023). "To interrogate if SCEL overexpression in tumor cells can influence adjacent stromal cells that alter TME favorable for tumor progression, we used a liquid suspension array method and found that IL-6, IL-8, IL10, and MIP-1a were markedly downregulated when SCEL was knocked down in GBC-SD." (PMID 33414368, 2021). "Thus, our data suggest that DSCAM-AS1 might also have a tumor-promoting role in endometrial carcinogenesis via activation of sciellin." (PMID 35885035, 2022). "Subsequently, SCEL expression in 7 pairs of fresh GBC tissues and the tumor-adjacent normal tissues were analyzed using Western blot analysis and RT-PCR." (PMID 33414368, 2021). "The comparison of SCEL protein expression in TNBC and non-TNBC tumor tissues revealed a significant upregulation of SCEL expression in the TNBC tissues as compared to the non-TNBC tissues." (PMID 38037106, 2023). "SCEL upregulation was correlated with T staging, TNM stages, and poor survival of tumor patients." (PMID 33414368, 2021). "SCEL knockdown reduced the speed of tumor growth, but did not completely stop the growth of L2 cells." (PMID 27013588, 2016).
SCEL also shares sentences with these, for which no sentence is quoted: asthma (1 paper); cervical cancer (1); chorioamnionitis (1); colon cancer (1); endometrial cancer (1); kidney cancer (1); thyroid cancer (1); triple-negative breast carcinoma (1); urinary bladder cancer (1).